ENSG00000288637 (novel protein)
Gene: Protein-coding gene on chromosome 4 (153,152,435 to 153,415,081, forward strand). Ensembl gene ENSG00000288637.
Genetic constraint (gnomAD): Loss-of-function variants: 29 observed, 76.67 expected, observed/expected ratio (o/e) 0.38, 90% interval 0.28 to 0.52. Missense variants: 723 observed, 1,064.8 expected, observed/expected ratio (o/e) 0.68, 90% interval 0.64 to 0.72. Synonymous variants: 373 observed, 406.49 expected, observed/expected ratio (o/e) 0.92, 90% interval 0.84 to 1.